BCHE (butyrylcholinesterase)
Diseases named in the same sentence as BCHE in open-access papers (continued):
Sharing a sentence is not in itself a finding about the gene and the disease.
cancer (42 papers, 2006 to 2025). A tumor composed of atypical neoplastic, often pleomorphic cells that invade other tissues. "BCHE appears to play a predictive role in the survival of cancer patients and is associated with disease progression." (PMID 40751365, 2025). "On the basis of the results, it was determined that compound 3 featured a reactive profile and powerful anti-enzyme activity, making it a potential new therapeutic strategy against AChE and BChE-associated malignancies." (PMID 36226116, 2022). "In this study, all liver parameters, i.e. GGT, AST, ALT, BChE, albumin and bilirubin were significant risk predictors for all-cause mortality in the total cancer patient cohort." (PMID 29113384, 2017). "Expression of BChE was significantly lower in PC tissues (p < 0.001) across multiple cancer types, suggesting that BChE downregulation may be linked to PC development or progression." (PMID 40678419, 2025). "Furthermore, an association of decreased BChE levels and advanced tumor stage, cancer cachexia, and poor survival in patients suffering from other gastrointestinal, gynecologic, and urologic malignancies has been described earlier." (PMID 37280384, 2023). "There is a strong correlation between BCHE gene mutations and cancers and other diseases." (PMID 35915658, 2022). "BChE has been associated with sustaining cell proliferation in development and cancers." (PMID 28118357, 2017). "BChE could as well as be another marker for the extent of systemic inflammation, and based on its more robust association with nutritional status, also a more sensitive indicator of nutritional decline associated with worse prognosis in cancer patients." (PMID 29113384, 2017). "Consistently, lower BChE mRNA levels (p = 0.023) in PC patients with new tumor development following initial treatment highlight the potential importance of this gene in cancer progression or drug resistance." (PMID 40678419, 2025). "Analysis of publicly available databases showed reduced BChE mRNA levels in patient samples across various cancers, including PC." (PMID 40678419, 2025). "In 34 kinds of cancer, BCHE expression was a significant upregulation in seven tumors and downregulation in 24 tumors, such as COADREAD (T = 380, N = 359) statistical significance (p < 0.0001)." (PMID 40751365, 2025). "Noteworthy to highlight are the dual selective BChE inhibition/anticancer activities of the nucleosides 10 and 11, which make them promising dual-indication lead compounds for both AD and cancer." (PMID 40430552, 2025). "The high concentration of oleic acid, alongside moderate butyrylcholinesterase (BChE) inhibition and strong cytotoxic effects on various cancer cell lines, highlights its potential as a therapeutic agent." (PMID 39512543, 2024). "These polyynes exhibit a wide range of activities ranging from allelopathic to butyrylcholinesterase (BChE) inhibitors to antifungal and antimicrobial and even potential anti-cancer drugs." (PMID 39770033, 2024). "Some other proteins of interest include the surface protein FN1 and the enzyme butyrylcholinesterase (BCHE), both being known as unfavorable prognostic markers for different cancers along with EphA2." (PMID 37637064, 2023). "In 20 kinds of cancer, BCHE expression was lower than normal; in contrast, its expression was high in 7 kinds of cancer." (PMID 35915658, 2022). "The inhibition of hAChE/human recombinant BChE (hBChE), the antiproliferative activity on cancer cells, and the ability to cross the BBB suggest the high potential of biscoumarin derivatives." (PMID 33917200, 2021). "Paulowniatomentosa, also shows cytotoxic activity against several human cancer cell lines and inhibit the effects of human cholinesterase, butyrylcholinesterase, and bacterial neuraminidases." (PMID 32802899, 2020). "Uni- and multivariate survival analyses were performed to assess the association between decreased serum BChE levels and progression-free (PFS), cancer-specific (CSS), and overall survival (OS)." (PMID 30737542, 2019).
cancer (continued). "As to now, there are no data regarding the predictive value of liver parameters, especially BChE or albumin, in an unselected cohort of cancer patients." (PMID 29113384, 2017). "Systemic inflammation is a host reaction to carcinogenesis or cancer progression and serum levels of butyrylcholinesterase (BChE) have been reported to reflect the presence of inflammation and other clinical conditions." (PMID 27924136, 2016). "A comparison of the changing levels of AChE and BChE mRNAs in carcinomas according to their anatomical location also showed differences." (PMID 25956553, 2015). "In cancer, the reduction of BChE parallels its decline in inflammatory conditions." (PMID 40678419, 2025). "This study also analyzed BCHE gene expression in cancer and normal tissues." (PMID 40751365, 2025). "Additionally, The Cancer Genome Atlas (TCGA) analyses identified BChE as a significant posttreatment neoplasm marker in PC." (PMID 40678419, 2025). "Moreover, advanced cancer is often accompanied by mild to moderate inflammation and varying degrees of protein–energy malnutrition (PEM), which leads to a reduction in plasma BChE levels and an elevated risk of mortality." (PMID 40282999, 2025). "BCHE is emerging as a promising biomarker for cancer diagnosis." (PMID 40751365, 2025). "Although low serum BChE levels have been documented in various cancers, its role in chemotherapy resistance remains unclear." (PMID 40678419, 2025). "Given its involvement in metabolic regulation and detoxification, BChE may influence cellular stress responses—processes that cancer cells frequently reprogram to support survival and therapy resistance." (PMID 40678419, 2025). "We analyzed pan‐cancer data from TCGA and GTEx to evaluate BCHE expression." (PMID 40751365, 2025). "In the first place, we examined pan-cancer data from TCGA and GTEx to assess BCHE expression." (PMID 35915658, 2022). "In addition, low serum BChE levels seem to be indicative of advanced tumor stage and poor prognosis in various forms of cancer, including gastric, renal, upper urinary tract, prostate, and head and neck cancer." (PMID 30737542, 2019). "The data clearly show that plasma levels of BChE and albumin are powerful predictors for all-cause mortality in an unselected treatment-naïve cancer patient cohort without manifest hepatic involvement irrespective of tumor type or stage." (PMID 29113384, 2017). "Decreased serum BChE and albumin levels are associated with increased all-cause mortality in treatment-naïve cancer patients without a manifest malignant hepatic involvement irrespective of tumor entity or stage." (PMID 29113384, 2017). "For example, BChE could have a role in cell proliferation during embryonic development and in cancers." (PMID 28118357, 2017). "The aim of this study was to investigate whether all liver parameters including BChE and albumin have the ability to predict long-term mortality in a treatment naïve cancer patient cohort independently from a malignant hepatic involvement." (PMID 29113384, 2017). "For the case of BCHE, it could look like the BCHE protein was locally more expressed in cancer tissue." (PMID 28837649, 2017). "Moreover, nutritional support in cancer patients resulted in augmented BChE levels parallel to an increase in body weight." (PMID 29113384, 2017). "AChE and BChE activity was measured in serum from cancer patients and in age-matched control group." (PMID 25956553, 2015). "In addition, BChE levels seem to correlate with cancer activity and nutritional status in ccRCC patients." (PMID 24741368, 2014). "Indeed, the use of BChE as a biomarker could aid in assessing the efficacy of cancer treatments and tracking disease progression." (PMID 40678419, 2025).
cancer (continued). "Investigating the differences in BChE expression levels between stromal and cancer cells in drug-refractory patient tissues and correlating these differences with disease progression could provide valuable insights into the role of BChE in cancer drug resistance." (PMID 40678419, 2025). "In addition, our study extends the prognostic value of plasma BChE and albumin for all-cause mortality in an unselected treatment-naïve cancer patient cohort irrespective of tumor entity or stage." (PMID 29113384, 2017). "BChE levels may correlate with cancer activity and nutritional status in ccRCC patients." (PMID 24741368, 2014). "S-AgNPs showed strong cytotoxicity against human hepato-cellular carcinoma cells (HepG2) and high enzyme inhibitory effect (IC50 values 27.5μg/ml for AChE and 22.60 μg/ml for BChE) compared to R-AgNPs and RS-AgNPs." (PMID 37014921, 2023). "Reduced BChE expression was observed in tumorigenic stem cell-like PC cells compared to non-stem cells, indicating potential alterations in BChE levels during cancer progression." (PMID 40678419, 2025). "The antioxidant potentials of the optimized extracts were evaluated using DPPH, FRAP, TAS, TOS, and OSI parameters; anticholinesterase activities were measured against AChE and BChE enzymes; and antiproliferative activities were investigated in A549, MCF-7, and DU-145 human cancer cell lines." (PMID 40871471, 2025). "Our study demonstrated that BChE and albumin are robust prognostic factors for overall survival in treatment-naïve cancer patients without manifest hepatic involvement irrespective of tumor entity and stage." (PMID 29113384, 2017). "The negative correlation of BChE and albumin with the inflammatory markers in this study supports previous observations for cancer patients." (PMID 29113384, 2017). "A decrease in pretreatment serum BChE level has also been suggested as a useful prognostic parameter in advanced cancer patients with or without hepatic involvement." (PMID 24741368, 2014). "Plasma BChE levels have been shown to decrease in advanced cancer patients with or without hepatic involvement, despite the other liver function tests yielding normal results." (PMID 24741368, 2014). "The potent antioxidant activity and significant inhibition of AChE and BChE by the DMF fraction and the inhibition of cell growth by the EAF and DMF fractions of C. religosa focus on its prospect of affording an efficient treatment for AD and cancer, respectively." (PMID 40535822, 2025). "The GO and GSEA of this study suggested that upregulated BCHE was primarily related to transmembrane transport, signaling pathway, cell-cell adhesion, chromosome maintenance, and pathways regulating immune response which contained TGF-β signaling pathway and cancer immunotherapy by PD1 blockade." (PMID 35915658, 2022). "Similarly, preoperative BChE levels were an independent prognostic factor for overall survival in various cancers of non-liver origin." (PMID 29113384, 2017).
tumor (28 papers, 2006 to 2026). "BCHE has been implicated in tumor cell choline metabolism, potentially affecting their energy supply and signal transduction." (PMID 40107973, 2025). "The relative intensity of myristic acid is higher in BCa samples and the expression of its associated gene, BCHE, is lower in the tumor samples." (PMID 37256175, 2023). "BCHE expression was related to various tumor characteristics, and high BCHE expression was associated with a higher histological grade, type, and clinical stage than low BCHE expression." (PMID 35915658, 2022). "Lower serum BChE levels were associated with lower BMI (p < 0.001), advanced tumor stage (p = 0.04), poor treatment response (p = 0.002), the occurrence of disease recurrence (p = 0.003), and the risk of death (p < 0.001)." (PMID 30737542, 2019). "Of note, lower serum BChE levels were associated with lower BMI (p < 0.001), advanced tumor stage (p = 0.04), poor response to treatment (p = 0.002), the occurrence of disease recurrence (p = 0.003), and the risk of death (p < 0.001)." (PMID 30737542, 2019). "For this cohort the described association with tumor stage remained significant for BChE and albumin." (PMID 29113384, 2017). "Additionally, genetic alteration analyses revealed that BChE expression is linked to tumor mutation burden." (PMID 40678419, 2025). "Not only an association of advanced tumor stage or enlarged tumor mass and chronic inflammation has been described in previous studies, but also an association of ongoing systemic inflammation and decreased serum BChE." (PMID 37280384, 2023). "The mutations of BCHE were also significantly related to the tumor immune system." (PMID 35915658, 2022). "In addition, we observed low serum BChE levels to be associated with advanced tumor load, poor response to treatment, and a low BMI." (PMID 30737542, 2019). "Additionally, low serum BChE levels were associated with advanced tumor stage, poor response to treatment, and a risk of recurrence and death." (PMID 30737542, 2019). "Moreover, tumours with low AChE activity and high BChE activity were associated with shorter patient overall survival." (PMID 25956553, 2015). "Therefore, lower BChE levels in advanced tumor stages may be caused by an underlying chronic infection." (PMID 30737542, 2019). "Inhibition potential was tested on the cholinergic enzymes acetylcholinesterase and butyrylcholinesterase, as well as Na+, K+-ATPase, an enzyme commonly overexpressed in tumours." (PMID 39684786, 2024). "Diminished systemic serum butyrylcholinesterase (BChE), a biomarker for chronic inflammation, cachexia, and advanced tumor stage, has shown to play a prognostic role in various malignancies." (PMID 37280384, 2023). "In a sensitivity analysis, backwards regression identified the interaction between preoperative BChE and neoadjuvant chemotherapy (p = 0.04, HR 0.92, 95% CI: 0.84–1.0), tumor stage, and lymph node ratio as the most important predictive factors for DFS." (PMID 37280384, 2023). "Sangerbox tools were used to delve into the relations between BCHE expression and tumor microenvironment, including microsatellite instability (MSI), tumor neoantigen count (TNC), and tumor mutation burden (TMB)." (PMID 35915658, 2022). "In multivariate analysis, tumor stage, tumor grade, administration of chemotherapy, bilirubin levels and a low BChE activity (hazard ratio: 1.42, 95% confidence interval: 1.10–1.82; p = 0.006) were identified as independent prognostic factors." (PMID 32375339, 2020). "BChE is regarded as sensitive marker for nutritional decline, a condition characteristic of advanced tumor load and shorter survival." (PMID 30737542, 2019). "Lower BChE activity levels in tumours with respect to their ANCT correlated with smoking (p < 0.001), alcohol consumption (p < 0.001), poorer differentiation grade (p = 0.002) and advanced clinical stage (p = 0.002)." (PMID 25956553, 2015).
tumor (continued). "The information relative to AChE and BChE involvement in cell proliferation and differentiation makes it possible that ChEs take part in tumour development." (PMID 25956553, 2015). "A possible pathological significance for the changing ChE activity was examined by comparing AChE and BChE activities in tumours and their clinico-pathological parameters." (PMID 25956553, 2015). "Afterwards, considering that the expression of AChE and BChE genes frequently changes with development and/or proliferation states, the possibility remained that tumours with distinct differentiation grading displayed unequal patterns of AChE or BChE mRNAs." (PMID 25956553, 2015). "As for BChE activity, patients with high tumour BChE activity (>2.967 mU/mg protein) had a poorer prognosis relative to both OS (p = 0.024) and DFS (p = 0.038)." (PMID 25956553, 2015). "Regarding analyses with overall survival as endpoint, BChE (p < 0.003), clinical tumor stage (p < 0.001), preoperative UICC classification (p < 0.001), grading (p < 0.001), pT (p < 0.001), pN (p < 0.003), and lymph node ratio (p < 0.001) were significantly related." (PMID 37280384, 2023). "In the univariable models, preoperative BChE (p < 0.001), clinical tumor stage (p < 0.001), preoperative UICC classification (p < 0.001), grading (p < 0.001), pT (p < 0.001), pN (p < 0.017), and lymph node ratio (p < 0.001) were significantly associated with disease-free survival." (PMID 37280384, 2023). "Different levels of BCHE expression in different tumor types might reflect distinct functions and mechanisms." (PMID 35915658, 2022). "In addition, serum BChE levels were found to be inversely correlated with tumor stage, suggesting an increase in tumor load to either impair the enzyme’s production or to increase its consumption." (PMID 30737542, 2019). "BChE and albumin were decreasing with progressive disease state reflected by tumor stage." (PMID 29113384, 2017). "This paradox might arise among other causes from decreased translation efficiency, shorter half-life of BChE protein in tumours, or faster release of secretion-destined BChE tetramers." (PMID 25956553, 2015). "The median follow-up time was 29.04 months (range 6–60 months), and a cut-off value of the 50th percentile of AChE (1.801 mU/mg protein) and BChE (2.967 mU/mg protein) was set-up when comparing activity values in tumours with OS and DFS rates of the study population." (PMID 25956553, 2015). "Additionally, Alb and BCHE levels are related to tumor recurrence." (PMID 39658717, 2025). "Additionally, the identification of BChE as a posttreatment neoplasm marker, derived from data mining analyses, suggests it might serve as a biomarker for tracking disease progression in PC." (PMID 40678419, 2025). "Thus, elevated BChE expression may provide tumor cells with a protective mechanism against such agents." (PMID 41226363, 2025). "However, this retrospective study only included PC patients at recurrence following curative resection, whereas our study explored a cohort consisting of PC patients at primary diagnosis across all tumor stages, establishing the BChE activity as a prognostic marker in a broader patient spectrum." (PMID 32375339, 2020). "Furthermore, BCHE expression levels may vary according to tumor stage." (PMID 40107973, 2025). "Results demonstrated that BCHE was low expressed in the tumor tissues of BLCA, BRCA, LUAD, and LIHC, but considerably expressed in the tumor tissues of GBM, HNSC, and KIRP." (PMID 38357546, 2024). "Bioinformatics analysis revealed that APOA1, BCHE, and STARD5 were significantly expressed in normal samples, while CYP19A1 and PLA1A were considerably expressed in tumor samples in the TCGA-STAD cohort." (PMID 38357546, 2024). "First of all, we obtained hub genes by taking the intersection between DEGs of TCGA and GEO,finding that BCHE, MAL and ASPM are tumor-related genes and can be used as potential biomarkers in EC treatment." (PMID 32099532, 2020).
tumor (continued). "Notably, BCHE is overexpressed in GBM tissues; its downregulation suppresses tumor cell proliferation, migration, and invasion." (PMID 40626539, 2025). "Although a correlation of advanced tumor stage and diminished BChE was observed, UICC stage did not play a significant role in patient’s prognosis in our results." (PMID 37280384, 2023). "BCHE, MAL and ASPM are tumor-related genes and can be used as potential biomarkers in EC treatment." (PMID 32099532, 2020). "Our findings suggested that ache mutants exhibited larger tumor volumes in comparison with healthy siblings regardless of the cell line used although they showed differential cholinesterase (ACHE/BCHE) expression." (PMID 29371671, 2018). "In accordance to previous studies, we found decreasing BChE and albumin levels with progressing tumor stage for both the total cohort and patients without hepatic involvement." (PMID 29113384, 2017). "Meanwhile, BChE expression was up-regulated regardless of the tumour histological grade." (PMID 25956553, 2015).